CALB2 (calbindin 2)
Diseases named in the same sentence as CALB2 in open-access papers (continued):
Sharing a sentence is not in itself a finding about the gene and the disease.
tumor (continued). "In 138 pairs of matched cancer and adjacent tissues, the proportion of CALB2+, CK19+CALB2+, and FAP+CALB2+ cells significantly increased in tumor tissues." (PMID 39358777, 2024). "Similar to CALB2, EMT, hypoxia, and inflammatory response pathways were also significantly enriched in tumor tissues with high CXCL14 expression." (PMID 39358777, 2024). "We concluded that CALB2 protein level was significantly correlated with serum CEA level, tumor differentiation, lymphatic metastasis, distant metastasis, and TNM stage." (PMID 37497410, 2023). "To further analyze the prognostic value of CALB2 and GPX3 in pan-cancer, we compared the expression levels of CALB2 and GPX3 in 32 tumor tissues and paraneoplastic tissues from TCGA and GTEx data." (PMID 37664836, 2023). "CALB2 expression in the CRC GSE12945 dataset (PMID: 19399471; probe ID: 20542 s at) was analysed for stage 3 tumours and combined staging." (PMID 21629658, 2011). "To further resolve the pathways potentially regulated by CALB2 and GPX3 in the TCGA dataset, we compared the pathways with significantly enriched pathways in tumor tissues and paraneoplastic tissues by GSVA method and calculated the GSVA scores of all pathways." (PMID 37664836, 2023). "The results showed that CALB2 and GPX3 were highly expressed in most tumor tissues." (PMID 37664836, 2023). "Accumulating studies indicated that tumor development was closely related to metabolic and signaling pathways in the organism, we extracted 172 metabolic and signaling-related pathways in the organism among KEGG pathways and calculated their correlations with CALB2 and GPX3." (PMID 37664836, 2023). "Finally, to explore whether CALB2 is essential for CAFs to fuel tumor growth in vivo, we established patient-derived organoid xenograft (PDOX) mouse models using human PDAC organoids that overexpressed luciferase, co-injected with control or CALB2+ CAFs." (PMID 39358777, 2024). "Although fluorouracil (5-FU) treatment reduced the mRNA and protein expression of CALB2 in CRC, their expression levels were not quantified and compared in tumor and normal tissues." (PMID 35836930, 2022).
cancer (15 papers, 2011 to 2026). A tumor composed of atypical neoplastic, often pleomorphic cells that invade other tissues. "Co-culture systems containing cancer-associated fibroblasts (CAFs) and patient-derived organoids (PDOs) in vitro and in vivo were employed to elucidate the effects of CALB2-activated CAFs on PDAC malignancy." (PMID 39358777, 2024). "CALB2 encodes a Ca2+ binding protein that was intimately associated with cancer." (PMID 37664836, 2023). "CALB2 was highly expressed both in CAFs and cancer cells and correlated with an unfavorable prognosis and immunosuppressive TME in PDAC patients." (PMID 39358777, 2024). "To enhance data credibility, we used a tissue microarray (TMA) cohort containing 190 PDAC patients and conducted multi-color immunofluorescence staining to confirm the correlation between CALB2 and stromal CAFs and cancer cells." (PMID 39358777, 2024). "In turn, CALB2-activated CAFs upregulate CALB2 expression in cancer cells via IL6-STAT3 inflammatory signaling pathway and support PDAC growth and metastasis." (PMID 39358777, 2024). "CALB2 collaborates with hypoxia to activate iCAFs, which secrete IL6 to upregulate CALB2 expression in cancer cells via STAT3-mediated direct transcription." (PMID 39358777, 2024). "The CALB2-Ca2+-CXCL14 inflammatory axis confers highly metastatic capability upon cancer cells and further facilitates an inflammatory and immunosuppressive TME in PDAC." (PMID 39358777, 2024). "In cancer cells, CALB2 further activated Ca2+-CXCL14 inflammatory axis to facilitate PDAC metastatic outgrowth and immunosuppression." (PMID 39358777, 2024). "In cancer cells, CALB2-Ca2+-CXCL14 axis further promotes an inflammatory and immunosuppressive TME to facilitate PDAC metastasis." (PMID 39358777, 2024). "Abnormally overexpressed CALB2, either in CAFs or cancer cells, correlates with an unfavorable prognosis and immunosuppressive TME in PDAC patients." (PMID 39358777, 2024). "Taken together, CALB2 plays a crucial role in the activation of CAFs and their crosstalk with cancer cells, ultimately leading to the increased growth and malignancy of PDAC." (PMID 39358777, 2024). "In the PDOX model co-transplanted with human PDAC organoid and CALB2+ CAFs, we observed that the IHC intensity of CALB2 is not only much higher in stromal CAFs than in the control, but also in cancer cells." (PMID 39358777, 2024). "CALB2 is upregulated in cancer cells by IL6-STAT3 inflammatory signaling-mediated direct transcription." (PMID 39358777, 2024). "The results above showed that co-culture with CALB2+ CAFs or treatment with rhIL6 resulted in a significant increase in both CALB2 protein and mRNA expression in cancer cells." (PMID 39358777, 2024). "Altogether, CALB2 is overexpressed in both cancer cells and CAFs in human PDAC, and correlates well with the immunosuppressive and desmoplastic TME and poor survival." (PMID 39358777, 2024). "In turn, CALB2-activated CAFs upregulated CALB2 expression in cancer cells through IL6-STAT3 signaling-mediated direct transcription." (PMID 39358777, 2024). "CALB2 is generally considered an oncogenic gene and a poor prognostic factor in current cancer research." (PMID 39358777, 2024). "Based on correlation analysis using TCGA pan-cancer transcriptome data, we observed a positive correlation between CALB2 expression and CAF infiltration across nearly all tumors." (PMID 39358777, 2024). "MiR-335 can influence apoptosis, proliferation, migration, and invasion of cancer cells through various target genes involved in different signaling pathways, including CALB2, and is often dysregulated in different cancer types." (PMID 38203360, 2023). "Nevertheless, the roles of HOXC6, SERPINE1, FABP4, SCG2, and CALB2 in tumorigenesis, cancer immunity, and ICB treatment are poorly understood." (PMID 35836930, 2022). "Additionally, CALB2 overexpressed in cancer cells and CAFs both strongly correlated with a reduced median overall survival (OS) of PDAC patients." (PMID 39358777, 2024).
cancer (continued). "Additionally, we revealed an inflammation-dependent cyclical mechanism by which CALB2-activated CAFs in turn upregulate CALB2 expression in cancer cells." (PMID 39358777, 2024). "Given its overexpression in cancer cells, we reasoned that CALB2 might also function in cancer cells." (PMID 39358777, 2024). "Next, to investigate whether IL6-dependent STAT3 activation is essential for CALB2 expression in cancer cells, various concentrations of stattic (MCE, #HY-13818), a potent STAT3 inhibitor, were added to the cancer cells with rhIL6 treatment." (PMID 39358777, 2024). "To ask whether CALB2 overexpression is associated with the immunosuppressive TME, we first analyzed the correlations between CALB2 and the steps of the cancer immunity cycle." (PMID 39358777, 2024). "our pan-cancer analysis similarly established that CALB2 probably served as prognostic biomarker for multiple cancer species, thus illustrating that GEM-CALB2 might be promising for novel therapeutic modalities in cancer." (PMID 37664836, 2023). "A mouse Calb2 promoter fragment (−115/+54bp) was shown to be active in neuronal and cancer cells." (PMID 26848772, 2016). "Given the pro-apoptotic function of CALB2, we hypothesised that cancer patients with higher levels of CALB2 would have a better prognosis." (PMID 21629658, 2011). "The present study proposes a pro-apoptotic role for CALB2 which may highlight cancer-specific functions for CALB2 that are relevant in the context of chemotherapy treatment." (PMID 21629658, 2011). "Hence, we reasoned that CALB2 overexpression in cancer cells might correlate with the ability of CALB2+ CAFs to act on cancer cells." (PMID 39358777, 2024). "However, the physiological function of CALB2 in cancer cells remains to be elucidated." (PMID 21629658, 2011). "Moreover, down-regulation of CALB2 in response to 5-FU may represent an intrinsic mechanism of resistance to this anti-cancer drug." (PMID 21629658, 2011). "In addition, acute down-regulation of CALB2 in response to 5-FU treatment may represent a mechanism of 5-FU resistance in cancer cells." (PMID 21629658, 2011). "CALB2-Ca2+-CXCL14 inflammatory axis confers highly metastatic and immunosuppressive ability on cancer cells." (PMID 39358777, 2024). "The activated STAT3 directly binds to the gene promoter of CALB2 and regulates CALB2 transcription, indicating that IL6-STAT3 inflammatory signaling is responsible for CALB2 upregulation in cancer cells." (PMID 39358777, 2024). "Next, the K-M survival curves demonstrated the prognostic status in the high- and low-expression groups of CALB2 and GPX3 in 26 cancers." (PMID 37664836, 2023). "Cancer development was observed by the modulation of genes involved in cell death (HIST1H1T, CASP14, and DNAJC3), cancer related genes (WNT8A and CASC8), gene expression (transcription) (ZNF570 and ZFP42), and metabolism of proteins (CALB2 and KLHDC3)." (PMID 31797963, 2019). "In several studies aiming at driving suicide gene expression in cancer cells, a 2.2kb human CALB2 promoter fragment was reported not to be specific for cancer cells." (PMID 26848772, 2016). "In addition, we found that CALB2 and GPX3 could also be considered as prognostic biomarkers in pan-cancer." (PMID 37664836, 2023).
psychiatric disorder (1 paper, 2025). A disorder characterized by behavioral and/or psychological abnormalities, often accompanied by physical symptoms. "Concordant with the increased inflammatory signal, there was a downregulation in mRNA expression of genes linked to neurodevelopment and myelination, neurotransmitter regulation, and psychiatric disorders including calcium binding Calb2 and S100b, as well as SNAP25, Pvalb, MAG, Olig1, and Olig2." (PMID 40059770, 2025).
CALB2 also shares sentences with these, for which no sentence is quoted: depression (2 papers); epilepsy (2); infection (2); ovarian carcinoma (2); acute myeloid leukaemia (1); adenocarcinoma (1); cervical cancer (1); colitis (1); colon adenocarcinoma (1); coronary artery disease (1); dominant optic atrophy (1); essential thrombocythaemia (1); glioma (1); hematologic malignancies (1); Hirschsprung disease (1); leiomyosarcoma (1); liver disease (1); medullary carcinoma of the colon (1); myeloid neoplasm (1); myeloproliferative neoplasm (1); neurodegenerative disease (1); neurodevelopmental disorder (1); neurological disorders (1); plasmacytoma (1); pleural mesothelioma (1); pleural plaques (1); prostate carcinoma (1); rectal cancer (1).